LEP (leptin)
Diseases named in the same sentence as LEP in open-access papers (continued):
Sharing a sentence is not in itself a finding about the gene and the disease.
cardiac hypertrophy (continued). "Finally, leptin deficiency leads to ventricular hypertrophy and heart failure." (PMID 22853195, 2012). "Endogenous leptin exerts pro-hypertrophic effects on the heart, whereas exogenous leptin has been shown to markedly attenuate cardiac hypertrophy and fibrosis by modulating the cGAS-STING signaling pathway and Opa1-mediated mitochondrial fusion." (PMID 41020872, 2025). "With respect to leptin, however, there is a paucity of data linking leptin-induced cardiac hypertrophy to JAK/STAT activation." (PMID 38256208, 2024). "Clearly, further work is required to delineate the precise effect and role of leptin in myocardial hypertrophy in various experimental models including those in which leptin or leptin signalling is modified through genetic manipulation." (PMID 38256208, 2024). "On the other hand, the increase in heart rate and blood pressure mediated by leptin can lead to increased myocardial workload, contributing to long-term cardiac hypertrophy (through sympathetic nervous system activation)." (PMID 38397015, 2024). "TGF- β1 is closely related to myocardial fibrosis, and leptin coincides with cardiac hypertrophy through binding of leptin to the short form leptin receptor in rat hearts." (PMID 38057836, 2023). "Leptin has been previously reported to protect against cardiac hypertrophy via attenuating cardiac TG accumulation." (PMID 35145478, 2021). "Animal models have helped to understand leptin signaling in the heart and both ob/ob and db/db mice show an age-dependent progression of hypertrophy, mostly effecting left ventricular (LV) mass and LV wall thickness." (PMID 32655492, 2020). "Another mechanism is related to leptin that mediates the process of cardiac hypertrophy in parts by the mitogen-activated protein kinase (MaPK p38), which regulates various cellular processes." (PMID 32032383, 2020). "We quantified plasma concentrations of leptin and adiponectin, as these adipocyte-mediated hormones have been demonstrated in vitro and in vivo to have direct effects on cardiac hypertrophy." (PMID 31842996, 2019). "It is possible that the potential effects of leptin to promote cardiac hypertrophy during pregnancy contributed to enhanced cardiac hypertrophy in HF-fed postpartum mice." (PMID 31842996, 2019). "Mice subjected to IR and cardiac leptin overexpression exhibited LV hypertrophy, dilation, and perivascular fibrosis." (PMID 30312306, 2018). "With respect to leptin and cardiac hypertrophy, clinical investigations have demonstrated that fasting plasma leptin concentrations are associated with increased myocardial wall thickness independent of body weight and blood pressure in hypertensive men." (PMID 23270329, 2012). "Furthermore, the mRNA levels of cardiac hypertrophy markers, such as ANF, BNF and β-MHC, were significantly upregulated in the myocardium in Plin5/leptin-DKO mice compared with Plin5-wild-type and leptin-deficient mice." (PMID 37667357, 2023). "In addition to metabolic, hemodynamic, and lipotoxic effects, also increased leptin concentrations promote myocardial hypertrophy and incident HF in obese individuals." (PMID 36684585, 2022). "In conclusion, it remains uncertain whether cardiac hypertrophy is due to leptin pro-hypertrophic action or is instead an effect of resistance to leptin antihypertrophic action on cardiac remodeling." (PMID 34603210, 2021). "Plasma leptin is directly proportional to the amount of adipose tissue; it is involved in regulating body energy balance and also presents pro-inflammatory and pro-oxidant properties, and promotes cardiac fibrosis and hypertrophy." (PMID 33142857, 2020). "Nevertheless, the effect of leptin in myocardial hypertrophy is debatable in the literature." (PMID 32354021, 2020). "Lean heart: Role of leptin in cardiac hypertrophy and metabolism." (PMID 32236321, 2020).
cardiac hypertrophy (continued). "Our results support the role of leptin as a deleterious factor for cardiac function and indicates that mitochondrial dysfunction could be a trigger for cardiac hypertrophy and failure." (PMID 30154842, 2018). "Administration of leptin, but not CR, reversed age-dependent cardiac hypertrophy in leptin-deficient ob/ob fat mice." (PMID 26673217, 2015). "Since GATA-4 is well known to promote cardiac hypertrophy, it is interesting to study whether leptin-induced vascular remodeling could be mediated by GATA-4, thus discovering a new role for GATA-4 in the vascular system." (PMID 26557089, 2015). "Importantly, overactivation of leptin signaling in hearts of LepRS1138 mice was accompanied by a pronounced cardiac hypertrophy, both at the organ and the single cardiomyocyte level, despite similar adiposity." (PMID 23841921, 2013). "Taken together, our findings suggest that hearts from diet-induced obese mice continue to respond to chronically elevated leptin levels and that increased systemic and/or local leptin and enhanced cardiac LepR activation contribute the development of cardiac hypertrophy." (PMID 23841921, 2013). "Indeed, studies have highlighted the role of leptin and insulin in the elongation of cardiac myocytes, ventricular hypertrophy, and heart failure." (PMID 23468899, 2013). "Although previous reports are divided on whether leptin has predominantly adverse or beneficial effects on cardiac hypertrophy, our results suggest a new local mechanism by which leptin directly affects cardiac remodeling in pressure-overloaded hearts." (PMID 23270329, 2012). "In this context, it is reasonable to consider that leptin may not directly cause myocardial hypertrophy and fibrosis, but rather, that these changes could represent a correlation." (PMID 39682585, 2024). "Therefore, leptin-mediated increase in heart rate and blood pressure may provoke an increase in myocardial workload, which contributes to cardiac hypertrophy over the long term." (PMID 32655492, 2020). "However, whether leptin promotes cardiac hypertrophy in vivo may be dependent on blood pressure, and leptin may have differential effects on blood pressure in humans versus mice." (PMID 31842996, 2019). "However, the findings support that inhibition of PPARβ/δ-associated pathways may interfere with central leptin’s beneficial effects in the heart, which may be relevant in patients with conditions like generalized lipodystrophy where leptin therapy is used to mitigate cardiac hypertrophy." (PMID 39199415, 2024). "For example, leptin treatment of cardiomyocytes from humans and neonatal rats has been found to induce TNF-α-/IL-6-mediated redox stress and cardiac hypertrophy." (PMID 36684585, 2022). "Leptin also significantly increased expression of α-skeletal actin and myosin light chain-2 (MLC-2), both upregulated in cardiac hypertrophy." (PMID 26064110, 2015). "As leptin-deficient mice are characterized by abnormal lipid metabolism and cardiac hypertrophy, we generated Plin5/leptin-double-knockout (DKO) mice and found that lactate levels were significantly elevated in the myocardia of Plin5/leptin-DKO mice compared with those of leptin-knockout mice." (PMID 37667357, 2023). "The levels of phosphorylated cofilin-2 are increased in myocardial hypertrophy through the activation of LIM-kinase (LIMK) by ROCK, which is induced by multiple neurohumoral factors, such as angiotensin II, endothelin 1 and leptin." (PMID 36428995, 2022). "Our findings suggest that hearts from obese mice continue to respond to elevated circulating or cardiac leptin, which may mediate cardioprotection via LepR-induced STAT3 activation, whereas signals distinct from LepR-Tyr1138 promote cardiac hypertrophy." (PMID 23841921, 2013). "Whether leptin contributes indirectly to cardiac hypertrophy via hemodynamic effects in humans is not clear." (PMID 31842996, 2019).
cardiac hypertrophy (continued). "The genetic ob/ob mouse model lacking leptin is grossly obese and develops elevated blood glucose and FGF21 levels, while exhibiting cardiac hypertrophy at six months of age46." (PMID 35513431, 2022).
heart failure (59 papers, 2010 to 2025). Inability of the heart to pump blood at an adequate rate to meet tissue metabolic requirements. "Some studies have shown that increased leptin levels in plasma are associated with adverse outcomes in heart failure and CAD." (PMID 36984571, 2023). "Leptin has diverse pathophysiological effects on heart failure, and high levels are associated with increased cardiovascular events." (PMID 37176525, 2023). "NT-proBNP, which is an established biomarker of heart failure, was significantly inversely associated with irisin (r = −0.420, p = 0.003) and leptin levels (r = −0.354, p = 0.015)." (PMID 36330203, 2022). "A positive association between REE and leptin was observed in cross-sectional studies involving 40 to 50 patients with chronic obstructive pulmonary disease (COPD) or heart failure (HF)." (PMID 35369060, 2022). "This may explain the younger age of onset of heart failure in South Asian than in Western individuals as data show that higher leptin and lower adiponectin levels are associated with activation of the RAAS system and volume overload." (PMID 39097697, 2024). "Increased levels of leptin were independently associated with a higher incidence of heart failure." (PMID 37176525, 2023). "High serum leptin levels are associated with pathological myocardial hypertrophy and ischemia, an increased risk of serious cardiovascular events, and a poorer prognosis in patients with heart failure." (PMID 35488267, 2022). "Based on these epidemiologic data, it remains unclear whether leptin is associated with the development of heart failure." (PMID 32655492, 2020). "Elevated levels of leptin have been associated with increased cardiovascular risk particularly with respect to heart failure and hyperleptinemia has been proposed as a potential marker for heart failure development." (PMID 22848545, 2012). "Thus, lower leptin levels may be associated with the loss of the protective effects of this adipokine, as reported in patients with heart failure." (PMID 31703113, 2019). "The second represents chronic responses to leptin exposure resulting in pathological changes such as cardiomyocyte hypertrophy, thus contributing to the development of cardiac pathology including heart failure." (PMID 38256208, 2024). "Although the role of leptin on the prognosis of heart failure is unclear, there is rising evidence that the role of leptin in glucose metabolism is important." (PMID 37176525, 2023). "Circulating leptin levels presage the development of heart failure in elderly people and a decline in the glomerular filtration rate in longitudinal studies." (PMID 36140169, 2022). "Laboratory tests in obese heart failure patients showed the lowest NT-proBNP concentrations, significantly higher leptin concentrations and higher leptin/adiponectin ratios." (PMID 36428528, 2022). "While leptin is secreted from adipose tissue, cardiac cells themselves can produce leptin and appear to synthesize more leptin in patients with heart failure, leading to the increase in local as well as systemic leptin." (PMID 33495937, 2022). "The elevated concentration of leptin is confirmed in patients with heart failure, both with reduced and preserved ejection fraction." (PMID 32198598, 2020). "Since we have shown that the magnitude of post-MI heart failure correlates with cardiac leptin expression level, therapeutic strategy to mitigate post-MI HF should target in situ cardiac leptin activity via local approach." (PMID 30312306, 2018). "In our study, serum leptin was reduced along with the NYHA grading, indicating its possible role in heart failure-associated appetite loss." (PMID 29155861, 2017). "Although the major source of leptin is adipose tissue, cardiomyocytes are also capable of synthesizing leptin, and increased cardiac leptin levels have been reported in mice or rats following coronary ligation or in patients with heart failure." (PMID 23841921, 2013).
heart failure (continued). "The role of leptin in the heart failure processes is still somewhat uncertain as both deleterious and beneficial roles have been proposed." (PMID 22848545, 2012). "The title or abstract search term ‘leptin’ was used in combination with ‘heart failure’ and ‘HF’." (PMID 40417460, 2025). "It is interesting to also note that ginseng, a Traditional Chinese Medication demonstrating excellent antihypertrophic effects as well as an ability to attenuate heart failure in animal models, can effectively inhibit leptin-induced hypertrophy in neonatal cultured rat ventricular myocytes." (PMID 38256208, 2024). "Moreover, leptin has been shown to contribute to myocardial remodelling by stimulating myocardial fibrosis, thus further contributing to the development of heart failure." (PMID 38256208, 2024). "Moreover, high plasma leptin concentrations have been used as predictors of increased severity of heart disease including heart failure; however, other reports showed an inverse relationship between plasma leptin levels and left ventricular mass." (PMID 38256208, 2024). "Here, we discuss mechanisms that potentially mediate leptin-induced cardiac pathological hypertrophy, which may contribute to the development of heart failure." (PMID 38256208, 2024). "Furthermore, SGLT-2i reduces blood leptin, increases adiponectin levels, and shows cardiovascular protective properties, in particular in cases of heart failure, by reducing the adipose accumulation in the myocardium." (PMID 37049856, 2023). "In this context, speculations about a possible interaction of leptin and neprilysin in heart failure, glucose and lipid metabolism are considered." (PMID 37176525, 2023). "Although the mechanism/s of leptin action in heart failure are not fully understood, one potential mechanism might be its effect on epicardial adipose expansion and on calcium handling in cardiomyocytes leading to impaired myocardial relaxation." (PMID 36140169, 2022). "Taken together, leptin exerts physiological effects that may be detrimental in states of cardiac dysfunction or heart failure." (PMID 32655492, 2020). "The data on leptin levels from previous studies vary in heart failure patients." (PMID 26147101, 2015). "It is enticing to study whether leptin could play a therapeutic role in the myocardium in cases of heart failure and ischemia." (PMID 26064110, 2015). "Although further studies are necessary, based on this finding it has been postulated that leptin may directly contribute to the development of heart failure in obese individuals." (PMID 22848545, 2012). "There is emerging evidence that leptin may contribute to cardiac pathology especially that related to myocardial remodelling and heart failure." (PMID 22848545, 2012). "Therefore, acute effects of leptin may provide a compensatory response to cardiac insults, such as ischemia or heart failure." (PMID 32655492, 2020). "Thus, it is likely that adiponectin plays an essential role in impaired metabolic signaling that is linked to heart failure progression including inflammation, muscle wasting, and poor nutrition in CVD patients receiving cardiovascular surgery, in contrast with leptin." (PMID 31703113, 2019). "Certainly we cannot rule out that the amount of transplanted fat was not sufficient to reverse heart failure, although the IR has been significantly improved with increasing plasma leptin levels." (PMID 33778025, 2021). "In obese individuals, elevated leptin may contribute to low-grade inflammation, rendering them more susceptible to cardiovascular diseases; whereas in dilated cardiomyopathy, leptin is a biomarker for the progression of heart failure independent of immune responses." (PMID 35069436, 2021). "In a prospective study of 4,080 men, aged 60–79 years, with no diagnosed heart failure followed for 9 years, increased BMI and circulating leptin levels were used as independent predictors for the incidence of heart failure." (PMID 32655492, 2020).
heart failure (continued). "In vitro, leptin induces cardiomyocyte hypertrophy involving MAPK and RhoA-GTP, which contribute to morphological and phenotypic changes in cardiac size, structure, function, and heart failure." (PMID 23924318, 2013). "However, in previous trials, the dynamics of leptin in heart failure without ARNIs were well described." (PMID 37176525, 2023). "In addition, elevated leptin levels have been reported in patients with dilated cardiomyopathy, which are used as a biomarker for the progression of heart failure independent of immune responses." (PMID 32655492, 2020). "Furthermore, a negative correlation was observed between the serum leptin level and the plasma BNP level, a marker of heart failure severity, in contrast to the relationship between the serum adiponectin concentration and the plasma BNP level." (PMID 31703113, 2019).